STAT3 (signal transducer and activator of transcription 3)
Diseases named in the same sentence as STAT3 in open-access papers (continued):
Sharing a sentence is not in itself a finding about the gene and the disease.
dermatitis (44 papers, 2012 to 2025). An inflammatory process affecting the skin. "The HIES have historically been defined by the triad of elevated IgE, dermatitis, and recurrent skin and lung infections and include diseases caused by mutations of STAT3, TYK2, PGM3, ZNF341, CARD11, and IL6ST." (PMID 33932191, 2021). "In the present study, we directly investigated the contribution of STAT3 to skin homeostasis and dermatitis by generating mice with conditional deficiencies in this protein in the skin." (PMID 34867936, 2021). "Mice with keratinocyte-specific STAT3 deficiency (termed Stat3 cKO mice) developed more severe DNCB-induced AD-like skin inflammation accompanied by skin barrier impairment, Staphylococcus-dominant microbial dysbiosis, more infiltrating type-2 inflammatory cells, and increased IL-4 levels." (PMID 38053996, 2023). "Thus, epidermal keratinocyte-specific STAT3 deficiency can aggravate AD-like skin inflammation in mice, possibly through TSLP dysregulation." (PMID 38053996, 2023). "Immunosuppressed mice with cutaneous deficiency in both STAT3 and filaggrin displayed rapidly progressing vaccinia disease, characterized by elevated local virus recovery, dermatitis, mucosal mast cell accumulation, and activin A overexpression in infected skin." (PMID 28081250, 2017). "In conclusion, our findings indicate that KRT6A plays a pivotal role in skin inflammation, primarily by activating the STAT3 pathway and promoting the production of downstream proinflammatory cytokines in keratinocytes." (PMID 40346694, 2025). "While STAT3-HIES-associated dermatitis is generally treatment-resistant, dupilumab appears to be effective in treating dermatitis in these patients." (PMID 41181176, 2025). "Here, by using mice with keratinocyte-specific deletion of STAT3, we provide relatively direct evidence for the potential inhibitory role of keratinocyte STAT3 in the pathogenesis of AD-like skin inflammation." (PMID 38053996, 2023). "In summary, our findings provide insights into the role of keratinocyte STAT3 in regulating AD skin inflammation." (PMID 38053996, 2023). "A recent report showed that epidermal Rora deletion alleviated imiquimod-induced psoriatic-like skin inflammations by attenuating the activation of nuclear factor-κB (NF-κB and STAT3 in keratinocytes)." (PMID 37373387, 2023). "Collectively, these results indicate that keratinocyte-specific STAT3 dysfunction exacerbated DNCB-induced AD-like skin inflammation." (PMID 38053996, 2023). "On the other hand, the majority of patients with DOCK8 and STAT3-AD (LOF) mutations developed eczema, dermatitis, and viral skin infections." (PMID 37237458, 2023). "Consistently, there was a significant increase in eosinophil number in Stat3 cKO mice with DNCB-induced AD-like skin inflammation." (PMID 38053996, 2023). "Taken together, these data suggest that epidermal barrier impairment was aggravated in Stat3 cKO mice with AD-like skin inflammation, accompanied by specific AMP insufficiency and Staphylococcus-dominant microbial dysbiosis." (PMID 38053996, 2023). "After topical 2,4-dinitrochlorobenzene (DNCB) treatment, Stat3 cKO mice developed worsened AD-like skin inflammation with increased Ki67+ cells, decreased filaggrin and loricrin expression, and downregulated S100A9 and LL37." (PMID 38053996, 2023). "We found that anti-TSLP antibody treatment attenuated DNCB-induced AD-like skin inflammation in Stat3 cKO mice, as the ear thickness and dermatitis score were significantly decreased." (PMID 38053996, 2023). "TSLP blockade attenuated DNCB-induced AD-like skin inflammation in Stat3 cKO mice, suggesting that keratinocyte-specific STAT3 dysfunction leads to TSLP-mediated skin inflammation in AD." (PMID 38053996, 2023). "More importantly, blockade of TSLP activity by TSLP neutralizing antibody markedly reduced AD-like skin inflammation in Stat3 cKO mice." (PMID 38053996, 2023).
dermatitis (continued). "We used dupilumab to treat severe dermatitis in a patient with STAT3-HIES and achieved satisfactory results." (PMID 38482457, 2023). "Altogether, our results suggest that A63 can ameliorate AD-like skin inflammation by inhibiting inflammatory cytokine production and STAT3/6 and Mitogen-activated protein kinase (MAPK) signaling and restoring skin barrier function." (PMID 35566102, 2022). "Partial improvements in dermatitis in HIES patients treated with hematopoietic stem cells have suggested that the role of STAT3 signaling in cells other than T cells is involved in the onset of dermatitis." (PMID 34867936, 2021). "Local skin inflammation caused by UVB irradiation is often associated with activation of NF-κB and STAT3 responsible for transcriptional regulation of diverse proinflammatory cytokines and enzymes, including COX-2 and iNOS." (PMID 34071363, 2021). "This dermatitis is thought to be attributed to defects in STAT3 signaling in type 17 helper T cell specification." (PMID 34867936, 2021). "It is characterized by severe dermatitis, a peculiar face, frequent infections, extremely high levels of serum IgE and eosinophilia, all resulting from a defect in the STAT3 gene." (PMID 33343952, 2020). "AD appears to be characterized by skin inflammation, barrier dysfunction, and chronic pruritus, which are all attributable to excessive activation of the IL-13/IL-4‒JAK‒STAT6/STAT3 axis and its associated immune reaction." (PMID 33233866, 2020). "It was reported that epidermal keratinocytes induce skin inflammation in the STAT3 overexpressed transgenic mice." (PMID 30430364, 2019). "Immunosuppressed, filaggrin-deficient mice, treated with the topical STAT3 inhibitor Stattic® prior to ACAM-2000 infection, demonstrated rapid weight loss, prolonged vaccinia burden in skin, and dermatitis." (PMID 28081250, 2017). "This suggests that β-Acetoxyisovalerylalkannin may alleviate skin inflammation by inhibiting the immune response mediated by the MAPK/STAT3 pathway." (PMID 41011121, 2025). "Additionally, DIDS-associated eczematous dermatitis is more consistent with typical AD compared to the eczematous dermatitis of STAT3-HIES." (PMID 41181176, 2025). "TSLP blockade significantly alleviated DNCB-induced AD-like skin inflammation in Stat3 cKO mice." (PMID 38053996, 2023). "In this study, we found that Stat3 cKO mice exhibited worsened AD-like skin inflammation characterized by a defective skin barrier, Staphylococcus-dominant microbial dysbiosis, more infiltrating immune cells, and an increased concentration of keratinocyte-derived TSLP." (PMID 38053996, 2023). "IL-22 also induces dermatitis and acanthosis by activating the STAT3-mediated IL-23 pathway." (PMID 34295334, 2021). "The excess expression of HF-specific keratin genes during the infant period was correlated with skin barrier dysfunction and the development of dermatitis, suggesting that STAT3 signaling in infant skin is crucial for maintaining skin barrier homeostasis to prevent dermatitis." (PMID 34867936, 2021). "In this study, immunofluorescence and qPCR analysis showed that MLT significantly reduced the infiltration of CD4+ T cells in rosacea-like dermatitis and suppressed the expression of Th1-related genes (IFN-γ, CCR5, CXCL9, CXCL10) and Th17-related genes (STAT3 and IL-20) in rosacea-like dermatitis." (PMID 34899707, 2021). "Thus, we next investigated how the defect in STAT3 signaling impacts the skin structure that leads to dermatitis." (PMID 34867936, 2021). "In this study, Staphylococcus dominance and corresponding transcriptomic alterations in the skin were found in Stat3 cKO mice with AD-like skin inflammation, suggesting that Staphylococcus-dominant microbial colonization may be trigger TSLP expression in Stat3 cKO mice." (PMID 38053996, 2023). "In addition, caffeic acid can suppress chronic UVB-induced dermatitis by inhibiting STAT3." (PMID 30430364, 2019).
dermatitis (continued). "Therefore, in this study, we evaluated the role of STAT3 in keratinocytes by generating mice with inducible keratinocyte-specific deletion of STAT3 and treating them with 2,4-dinitrochlorobenzene (DNCB) to induce AD-like skin inflammation." (PMID 38053996, 2023). "Furthermore, pinocembrin alleviated the severity of skin inflammation in imiquimod- (IMQ-) induced psoriatic dermatitis in mice, and the inhibitory effect may involve the HO-1/STAT3 pathway." (PMID 35116069, 2022). "Therefore, IDO2 might modulate STAT3 signaling, leading to decreased IL-17 expression and suppressing IMQ-induced dermatitis." (PMID 32752186, 2020). "Thus, TSLP may be an important determinant for promoting AD-like skin inflammation in the absence of keratinocyte STAT3." (PMID 38053996, 2023).
anaplastic large cell lymphoma (43 papers, 2008 to 2026). Anaplastic large cell lymphoma (ALCL) is a rare and aggressive peripheral T-cell non-Hodgkin lymphoma, belonging to the group of CD30-positive lymphoproliferative disorders, which affects lymph nodes and extranodal sites. "Abnormalities affecting more downstream signaling pathways are prominent in certain PTCLs, such as JAK/STAT3 signaling in anaplastic large cell lymphoma (ALCL) and STAT5B mutations in monomorphic epitheliotropic intestinal T-cell lymphoma (MEITL) and hepatosplenic T-cell lymphoma (HSTCL)." (PMID 35954378, 2022). "Interestingly, loss of SHP-1 in ALK-positive anaplastic large cell lymphoma is a direct consequence of the constitutive activation of STAT3 in these cells, as STAT3 plays a key role in promoting gene methylation and silencing of SHP1." (PMID 24995504, 2014). "The oncogenic fusion protein NPM-ALK drives anaplastic large cell lymphoma (ALCL) by activating the transcription factor STAT3." (PMID 41882193, 2026). "PKM2 has been shown to increase STAT3 activity and this facilitated the generation of anaplastic large cell lymphoma." (PMID 37190033, 2023). "SHP-1 silences the JAK/STAT pathway by inducing the dephosphorylation of both JAK and STAT3, and the loss of SHP-1 expression enhances JAK/STAT3 signaling in large cell lymphoma." (PMID 38203502, 2023). "Our study also found that most T/Natural Killer cells NHL expressed STAT-3, apart from Anaplastic Large cell lymphoma (ALCL) and Anaplastic Lymphoma Kinase-positive (ALK-positive)." (PMID 37175040, 2023). "Studies in nucleophosmin-anaplastic lymphoma kinase (NPM-ALK) positive (ALK+) T-cell lymphoma, a subgroup of anaplastic large cell lymphoma (ALCL), have implicated the transcription factor STAT3 as a central player in epigenetic regulation." (PMID 33310759, 2021). "In ALK + anaplastic large cell lymphoma, a strong correlation was found between the positive expression of p-Stat3 and the expression of Survivin." (PMID 34736477, 2021). "Of note, MYC with STAT3 transcriptionally regulates PD-L1 in ALK-negative anaplastic large cell lymphoma (ALCL)." (PMID 32549409, 2020). "Direct activation of STAT3 by the NPM-ALK chimeric protein, which plays a central pathogenic role in anaplastic large cell lymphoma (ALCL), promotes invasiveness of ALK-positive ALCL through induction of Twist-1." (PMID 31952344, 2020). "This molecule can reduce anaplastic large cell lymphoma proliferation through reducing Arf1-dependent signal transducer and activator of transcription 3 (STAT3) phosphorylation." (PMID 30884855, 2019). "In line with our findings, it was recently reported that in anaplastic large cell lymphomas (ALCLs) constitutively active Tyk2 fusion proteins are oncogenic by driving the STAT3 signaling pathway." (PMID 29162862, 2017). "Constitutive activation of β-catenin in anaplastic lymphoma kinase (ALK)-positive anaplastic large cell lymphoma elevates STAT3 expression and activation." (PMID 27036017, 2016). "Constitutive STAT3 activation and loss of SHP-1 in ALK-positive anaplastic large cell lymphoma have provided an example of a positive feedback loop." (PMID 24995504, 2014). "DnStat3 also inhibits Stat3 signaling in ALK-positive anaplastic large cell lymphoma by suppression of several Bcl-2 family genes." (PMID 18939995, 2008). "Finally, STAT3 is a useful classifier to differentiate the related hematopoietic malignancies HL and anaplastic large cell lymphoma." (PMID 29581848, 2018). "Similarly, total and active STAT3 levels were reduced by down-regulating β-catenin using siRNA in anaplastic large cell lymphoma cells." (PMID 23056515, 2012).
anaplastic large cell lymphoma (continued). "In anaplastic large cell lymphoma (ALCL) positive for anaplastic lymphoma kinase (ALK+), the aberrant overexpression of TIMP1 is directly associated with persistent STAT3 phosphorylation, thereby accelerating tumor progression." (PMID 41189944, 2025). "Increased STAT3 activity, GZMB expression, and CD30 expression are markers of anaplastic large cell lymphomas (ALCL) of T cell origin, which PWH are of increased risk of developing." (PMID 40627772, 2025). "Recent works showed that it cooperates with STAT3 to repress the transcription of tumor suppressor genes, thus interfering with its expression leads to transcriptional derepression, resulting in increased tumor cell death and reduced tumorigenic potential of anaplastic large-cell lymphoma." (PMID 38168833, 2024). "We and others have described the effects of the NPM-ALK/STAT3 axis on miRNA expression in ALK-positive anaplastic large cell lymphoma (ALCL)." (PMID 31878193, 2019). "Interestingly, by genetic profiling of breast implant associated anaplastic large cell lymphoma (BIA-ALCL), JAK2 was found to fuse with its downstream node STAT3, and this is also the first reported fusion fact in BIA-ALCL." (PMID 34680295, 2021). "This is consistent with previous study that targeting Stat3 signaling with dnStat3 suppresses cell-cycle-related genes, including cyclin-D1, in ALK-positive anaplastic large cell lymphoma." (PMID 18939995, 2008). "In anaplastic large cell lymphoma (ALCL), JAK1 and STAT3 are activated by high levels of cytokines, including IL-6." (PMID 31861597, 2019). "Additionally, several anaplastic large cell lymphomas (ALCL), of T cell origin, from PWH were found to have clonal proviral integrations in both STAT3 and the first intron of the src family tyrosine kinase LCK." (PMID 40627772, 2025). "This contrasts with other hematological malignancies, such as peripheral T-cell lymphomas, particularly the anaplastic large cell lymphoma (ALCL) form of the disease, where GOF mutations in STAT3, but not in STAT5B, have been observed." (PMID 38254802, 2024). "While STAT3 activation is induced by ALK fusion proteins in ALK-positive ALCL, it is induced by somatic mutations of STAT3 and JAK1 in 20% of ALK-negative anaplastic large cell lymphomas and 5% of primary cutaneous ALCL, whereas mutations in these genes have not been reported for CD30+ PTCL." (PMID 35330161, 2022).
Hypertension (43 papers, 2015 to 2025). The presence of chronic increased pressure in the systemic arterial system. "It has been observed that the JAK2/STAT3 pathway plays an important role in regulating age- and hypertension-associated rise of aortic stiffness." (PMID 35694160, 2022). "VSMCs can be transformed from contractile to synthetic types under the action of AngII‐induced STAT3 activation, which is the basis of VSMCs involvement in angiopathy caused by hypertension." (PMID 32627301, 2020). "Angiotensin II (AngII) binds to VSMCs’ AngII type 1 receptor to activate STAT3 in order to initiate the proliferation and migration of VSMCs, representing key effects in vascular lesions caused by hypertension." (PMID 32627301, 2020). "Activation of Ca2+/calmodulin-dependent kinase II (CaMKII), with transverse aortic constriction so as to mimic hypertension, caused phosphorylation of βIV-spectrin and the displacement of STAT3." (PMID 31069236, 2019). "JAK2/STAT3 activation, however, is tightly associated with AngII hypertension, even when caused by physiologic levels of AngII." (PMID 26486161, 2015). "p-STAT3 expression was associated with hypertension (p = 0.037)." (PMID 36473131, 2022). "We recently reported that mice with a global S727A mutation in STAT3 that precludes phosphorylation, devoid of a baseline phenotype, exhibit a loss of cardiac myocytes and diminished contractile function in response to the chronic stress of pressure overload due to hypertension." (PMID 27899891, 2016). "Nos3-/- hypertension downregulates STAT3's anti-inflammatory function and downstream chemokine expression." (PMID 39219951, 2024). "Our previous research has shown that STAT3 activation promotes the transcription of collagen-related genes, accelerating myocardial fibrosis in hypertension and DCM." (PMID 38794201, 2024). "According to studies, atorvastatin inhibits the IL-6/STAT3/endothelin-1 pathway in patients with spontaneous hypertension." (PMID 38855751, 2024). "For example, Faraci and colleagues demonstrated the involvement of STAT3 in angiotensin-induced vascular oxidative stress, endothelial dysfunction and hypertension and these effects were prevented by STAT3 inhibitor." (PMID 34911575, 2021). "There are data, that IL-6, produced by endothelial cells during hypertension, activates transcriptional factor STAT3 and induces transdifferentiation of the monocytes into CD16+ cells." (PMID 33854919, 2020). "Experimental evidence from both in vivo and in vitro studies established that activation of the JAK2/STAT3 pathway by Ang II plays a central role in the development of Ang II-dependent hypertension." (PMID 31703282, 2019). "Conversely, cardiomyocyte STAT3 is important for maintaining endothelial cell function and capillary integrity with aging and hypertension." (PMID 31069236, 2019). "STAT3 participates in mechanisms contributing to different chronic cardiac pathologies including hypertension-induced hypertrophy, fibrosis, and diabetic cardiomyopathy." (PMID 31709266, 2019). "In keeping with this, we also observed an increase in STAT3 activation the monocyte-derived cells in the aorta and kidney of mice with Ang II-induced hypertension." (PMID 29800237, 2018). "Rather, STAT3 is important for maintaining contractile function and metabolic homeostasis with hypertension." (PMID 30619368, 2018). "Examination of downstream mediators of IL-6 signaling, such as STAT3, has also revealed important insight into the role of IL-6 in experimental hypertension." (PMID 29186034, 2017). "Evidence also indicates that STAT3 is protective to the heart under chronic stress conditions, such as hypertension, pregnancy, and advanced age." (PMID 26664907, 2015). "Evidence also indicates that STAT3 is protective to the heart under chronic stress conditions, including hypertension, pregnancy, and advanced age." (PMID 26664907, 2015).